PTPN11 (protein tyrosine phosphatase non-receptor type 11)
Diseases named in the same sentence as PTPN11 in open-access papers (continued):
Sharing a sentence is not in itself a finding about the gene and the disease.
leukemia (continued). "Previous researches have confirmed that PTPN11 is a multifunctional non-receptor protein tyrosine phosphatase and associated with breast cancer, leukemia, lung cancer, hepatic cancer, stomach cancer as well as other cancers." (PMID 35802774, 2022). "Limited studies have addressed the contribution of Ptpn11 to KMT2A-driven leukemia in vivo." (PMID 31723831, 2019). "A contributing factor may be the high proliferative state of leukemia stem cells (LSCs) in pAML, with activated RAS signaling pathways, which could explain the elevated mutation frequencies in RAS pathway genes such as NRAS, KRAS, and PTPN11." (PMID 41294667, 2025). "Notably, this effect wasblocked by the S100a9/S100a8 inhibitor tasquinimod, indicating that the overproduction ofS100a9 and S100a8 by leukemia-initiating Ptpn11 mutant stem cells maycontribute to the recruitment of MDSCs to the microenvironment." (PMID 39149498, 2024). "Our data presented in this report does not suggest that the arginine transporter CAT3 is a useful therapeutic target for controlling cancer cell access to arginine because Pten loss or an oncogenic Ptpn11 mutation-driven leukemia development is not impacted by Slc7a3 depletion." (PMID 36528691, 2022). "Notably, mutated Ptpn11 is not the only cause of NS or NSML but also other haematological malignancies such as leukaemia." (PMID 36231062, 2022). "In addition, mutations in PTPN11 modulate serum HDL-C and are associated with hemostatic pathways such as platelet activation, aggregation, and sensitization, as well as major genes associated with hypertension, ischemic heart disease, leukemia, and breast cancer." (PMID 38060535, 2023). "In addition to leukemia-driving mutations, we have identified recurrent pathogenic mutations CRLF2 p.F232C (n = 7), TYK2 p.A413T (n = 7), JAK2 p.R683G (n = 4), KRAS p.G12D (n = 4), FLT3 p.Y842C (n = 3) and PTPN11 p.D61V (n = 3), previously frequently found in pediatric ALL." (PMID 34830809, 2021). "Moreover, upregulating the RAS pathway may be necessary but not sufficient for PTPN11 mutations to cause leukemias." (PMID 21799948, 2011). "Common mutations found in leukemia patients, such as ABL1, FGFR1, KRAS, MET, NOTCH1, and PTPN11, were also found among our patient population, although not universally." (PMID 37092520, 2023). "PTPN5 is in the same non-receptor Cys-based classical PTPs as PTPN1 and PTPN11, which promoted tumorigenesis in ovarian cancer, gastric cancer, prostate cancer, breast cancer, leukaemia, colorectal cancer and uveal melanoma." (PMID 32928212, 2020). "Shp2 encoded by PTPN11 (PTP, non-receptor type 11) gene is the first PTP to be identified as an oncogene and possesses an oncogenic role in the melanoma, leukemia, and lung and breast cancers." (PMID 32848131, 2020).
juvenile myelomonocytic leukemia (98 papers, 2011 to 2026). A myelodysplastic/myeloproliferative neoplasm of childhood that is characterized by proliferation principally of the granulocytic and monocytic lineages. "Somatic gain-of-function mutations of PTPN11 have been linked to several hematological malignancies, such as juvenile myelomonocytic leukemia (JMML), and to several types of human solid malignancies." (PMID 38510972, 2024). "Further, somatic PTPN11 variants occur in 34% of juvenile myelomonocytic leukemia and were also detected in other myelodysplastic syndromes, yet to a smaller extent." (PMID 37384296, 2023). "PTPN11 mutations have been linked to juvenile myelomonocytic leukemia (JMML), colorectal cancer, breast cancer, and HCC." (PMID 35057034, 2022). "Somatic gain of function mutations of PTPN11, the gene coding for SHP2, cause 35% of juvenile myelomonocytic leukemia (JMML) cases and are found in other hematologic malignancies and tumors." (PMID 34900129, 2021). "Somatic mutations in PTPN11 contribute to childhood malignancies, among which juvenile myelomonocytic leukemia (JMML) represents the archetypal disorder resulting from RAS signaling upregulation." (PMID 33116231, 2020). "PTPN11 gain-of-function mutation is the most common mutation found in patients with juvenile myelomonocytic leukemia and DNMT3A loss occurs in over 20% of acute myeloid leukemia patients." (PMID 29464054, 2018). "Somatic mutations of SHP2-encoding PTPN11 gene have been identified in patients with juvenile myelomonocytic leukemia, myelodysplastic syndrome, and acute myeloid leukemia." (PMID 27935860, 2017). "In NS patients with PTPN11 gene mutations, bleeding diathesis, juvenile myelomonocytic leukemia, cardiac defects, typical facies, cryptorchidism, and short stature were also reported to be more common than in patients without PTPN11 gene mutations." (PMID 27125300, 2016). "It has been reported that the mutation of PTPN11 is associated with high prevalence of juvenile myelomonocytic leukemias, neuroblastoma, melanoma, acute myeloid leukemia, breast cancer, lung cancer, and colorectal cancer." (PMID 26315028, 2015). "Diseases associated with PTPN11 include Noonan syndrome 1 and juvenile myelomonocytic leukemia." (PMID 41554047, 2026). "Notably, the E76K substitution is the most commonly identified somatic PTPN11 mutation in juvenile myelomonocytic leukemia." (PMID 38612443, 2024). "Similarly, it has been valuable in clarifying the progression of juvenile myelomonocytic leukemia (JMML) in patients with NS caused by mutations in PTPN11." (PMID 39201250, 2024). "In addition, somatic mutations in PTPN11 are found in roughly 35% of patients with juvenile myelomonocytic leukemia (JMML), a rare pediatric cancer." (PMID 37502916, 2024). "Also, identification of a PTPN11 mutation in a 4-year-old boy contributed to a change in his diagnosis from de novo AML to juvenile myelomonocytic leukemia (JMML) which evolved into AML." (PMID 28007021, 2016). "Three patients developed juvenile myelomonocytic leukemia (JMML) and one myelodysplasia; all of them carried PTPN11 variants (p = 0.055)." (PMID 40332000, 2025). "Gain-of-function PTPN11 mutations are the cause of more than 30% of juvenile myelomonocytic leukemia (JMML) and can be also found in other childhood malignancies." (PMID 38739228, 2024). "And the germline gain of function mutations in the PTPN11 gene is the cause of Noonan syndrome (NS) and juvenile myelomonocytic leukemia (JMML) via triggering Ras/Erk signaling pathway." (PMID 35802774, 2022). "Somatic activating mutations in PTPN11 are the most common cause of sporadic juvenile myelomonocytic leukemia (JMML), a rare but aggressive myelodysplastic and myeloproliferative neoplasm (MPN) occurring in young children." (PMID 35535491, 2022).
juvenile myelomonocytic leukemia (continued). "Mosaic variants in PTPN11 are associated with isolated juvenile myelomonocytic leukemia (JMML, a neoplasm NS patients are prone to develop), as well as other types of cancers, including astrocytoma (COSMIC Database: Genomic Mutation ID: COSM13036)." (PMID 35778969, 2022). "For example, RASopathies disorders such as NS and LS are correlated with specific cancer types such as Juvenile Myelomonocytic Leukemia (JMML), attributed to different mutation types of the PTPN11 gene." (PMID 32676024, 2020). "PTPN11 mutations are found in patients with Noonan Syndrome (NS), Leopard Syndrome (LS), juvenile myelomonocytic leukemia (JMML), acute myelogenous leukemia (AML) and various solid tumors." (PMID 29439552, 2018). "For example, mutations in PTPN11 has been reported to be associated with development of Juvenile Myelomonocytic Leukemia (JMML), acute myeloblastic leukemia (AML), and acute lymphoblastic leukemia (ALL)." (PMID 26768750, 2016). "He had PTPN11 and BCOR mutations and significant hepatosplenomegaly, suggestive of juvenile myelomonocytic leukemia (JMML) features." (PMID 40227821, 2025). "In juvenile myelomonocytic leukemia (JMML), a malignant myeloproliferative neoplasia manifests as splenomegaly with consequential thrombocytopenia; mutations in the PTPN11 (SHP2) gene leads to the hyperactivation of ERK and AKT signaling pathways." (PMID 41296464, 2025). "Catalytically activating heterozygous germline mutations in PTPN11 are associated with half of the cases of Noonan Syndrome (NS) and are also seen in blood cancers e.g. juvenile myelomonocytic leukemia (JMML), myelodysplastic syndromes and acute myeloid leukemia." (PMID 38965223, 2024). "Phenotypically related to pCMML, juvenile myelomonocytic leukemia (JMML) is a pediatric neoplasm often initiated by germline (CBL, NF1, PTPN11) or somatic (NRAS, KRAS, CBL, RRAS) RAS-activating mutations and is described as a bona fide RASopathy26,27." (PMID 34006870, 2021). "Mutations leading to activation of the protein tyrosine phosphatase SHP2 (encoded by the PTPN11 gene) are linked to a specific MPN form, juvenile myelomonocytic leukemia." (PMID 32849521, 2020). "Juvenile myelomonocytic leukemia (JMML) is a rare pediatric MDS/MPN overlap syndrome that is characterized by somatic mutations in NF1, CBL, NRAS, KRAS or PTPN11 that result in the activation of RAS/MAPK or JAK/STAT signaling." (PMID 31171568, 2019). "In addition, when a mutant allele of the gene Ptpn11 that is associated with juvenile myelomonocytic leukemia (JMML) is homozygously expressed in murine osteoprogenitors mice develop a myeloproliferative neoplasm reminiscent of JMML." (PMID 30279500, 2018). "Moreover, somatic mutations in PTPN11 occur in about 35% of the patients with juvenile myelomonocytic leukemia (JMML), a childhood myeloproliferative disorder (MPD)." (PMID 21799948, 2011). "PTPN11 missense mutations drive many human diseases, including hematopoietic malignancies such as acute myeloid leukemia (AML), acute lymphoid leukemia (ALL), and juvenile myelomonocytic leukemia (JMML)." (PMID 40631144, 2025). "Activating mutations in PTPN11 are most commonly associated with juvenile myelomonocytic leukemia but are not as well defined in other neoplasms." (PMID 38539499, 2024). "Also, mouse and patients cells with Juvenile Myelomonocytic Leukemia (JMML) bearing E76K SHP2 are more sensitive to LY6 than wild-type cells, highlighting its possible use for the treatment of PTPN11-associated malignancies." (PMID 36555586, 2022). "In addition, PTPN11 is mutated in the germline of patients with several developmental disorders (Noonan Syndrome [NS], and NS-related syndromes) and hematological malignancies (Juvenile Myelomonocytic Leukemia [JMML], and other childhood leukemias)." (PMID 34957126, 2021).
juvenile myelomonocytic leukemia (continued). "Treatment with ZOL for the control of hypercalcemia has not always been successful in a case of juvenile myelomonocytic leukemia (JMML) with PTPN11 mutation where the RAS pathway was dysregulated, this may however be due to the progression of the leukemia at the late time of treatment." (PMID 32529062, 2020). "Germ-line PTPN11 mutations cause ∼50% of Noonan syndrome (NS), which is characterized by short stature, skeletal abnormalities, cardiac defects, learning disabilities, and a predisposition to hematologic abnormalities, particularly juvenile myelomonocytic leukemia (JMML)." (PMID 25289670, 2014). "In hematologic malignancies, germline or somatic PTPN11 mutations drive leukemogenesis in juvenile myelomonocytic leukemia (JMML) and acute myeloid leukemia (AML), where SHP2 activity predicts disease severity and relapse risk." (PMID 41462587, 2025). "Additionally, mutations in PTPN11 have been found to be responsible for the development of Noonan syndrome (NS) and juvenile myelomonocytic leukemia (JMML) by triggering the RAS/MAPK signaling pathway." (PMID 38025540, 2023). "In addition, one third of patients with juvenile myelomonocytic leukemia without the syndrome harbor somatic mutations of Ptpn11, which were predicted to cause a gain of function in SHP2 that was proposed to act as an oncoprotein in these myeloid leukemias." (PMID 34746416, 2021). "White blood cells of juvenile myelomonocytic leukemia (JMML) patient with PTPN11 activating mutation exhibited significantly reduced viability in the presence of siRNAs targeting ACK1, indicating ACK1’s role in optimal SHP2 activation." (PMID 38965223, 2024). "In juvenile myelomonocytic leukemia (JMML) and AML cells, Ack1 activates PTPN11, and PTPN11-mutant JMML and AML cells are all sensitive to Ack1 inhibition." (PMID 36980241, 2023). "The FIP1L1::RARA fusion gene was first reported as a novel RARA-associated fusion gene in a 20-month-old child with juvenile myelomonocytic leukemia (JMML), no other mutations in N-Ras, K-Ras, or PTPN11 were detected." (PMID 36776354, 2022). "Rare NS patients progress to Juvenile Myelomonocytic Leukemia (JMML), which is fatal if not treated by bone marrow transplantation, somatic PTPN11 mutations are the single most common cause of sporadic JMML." (PMID 24628801, 2014). "Missense mutations in PTPN11 have previously been identified in patients with Noonan, Noonan-like, and LEOPARD syndromes, as well as in juvenile myelomonocytic leukemia." (PMID 21533187, 2011). "We hypothesize that the TET2- and PTPN11-related animals manifest features of FAB_M4/M5 rather than FAB_M0/M1/M2 since they are also hot mutations in chronic myelomonocytic leukemia and juvenile myelomonocytic leukemia (CMML and JMML)." (PMID 35771283, 2022).
breast carcinoma (95 papers, 2010 to 2026). "The protein tyrosine phosphatase SHP2 encoded by the proto-oncogene PTPN11 promotes breast cancer progression." (PMID 35739379, 2022). "Somatic gain-of-function mutations of PTPN11 are present in certain lung adenocarcinomas, breast cancer and gastric cancer." (PMID 27077911, 2016). "In addition, somatic GOF mutations within the PTPN11 gene have been found to commonly occur in certain solid tumours, such as colon carcinoma, breast cancer, lung cancer, thyroid cancer, melanoma, and neuroblastoma." (PMID 26673822, 2016). "PTPN11, for example, has been linked to pancreatic cancer, and PTPN4 has been linked to breast cancer." (PMID 37359510, 2023). "The phosphorylation levels of Y546 and Y584 of PTPN11 were lower in tumor tissues of breast cancer and HNSC." (PMID 35802774, 2022). "The phosphorylation degree of S562 of PTPN11 was substantially decreased in tumor tissues of breast cancer." (PMID 35802774, 2022). "Of these genes and proteins, three are classically upregulated in breast cancer, and these are associated with poor prognosis in breast cancer: CCDN1/cyclin D1, PTPN11/SHP2, and RPS6KB1/S6K1." (PMID 33204396, 2020). "TCGA and the Gene Expression Omnibus (GEO) databases were used to investigate the role of SHP2 in breast cancer and to evaluate the correlation between PTPN11/SHP2 mRNA expression and the prognosis of patients with breast cancer." (PMID 32944401, 2020). "Additionally, PTPN11 has been regarded as a vital oncogene that has been intensively studied in some cancers, such as breast cancer, and melanoma." (PMID 35802774, 2022). "Besides, the reduced PTPN11 phosphorylation levels were observed in breast cancer, clear cell RCC, head and neck carcinoma, and lung adenocarcinoma (LUAD)." (PMID 35802774, 2022). "In highly aggressive mouse models of breast cancer and melanoma, simultaneous suppression of CSF-1R and PTPN11 to activate macrophages and promote phagocytosis may be an effective strategy for macrophage-based immunotherapy." (PMID 35957898, 2022). "For instance, PTPN1 in hepatocellular carcinoma, PTPN11 in colon cancer and PTPN12 in breast cancer can be both tumor promoters and tumor suppressors based on different molecular pathways." (PMID 35957898, 2022). "Breast cancer, clear cell RCC, HNSC, and LUAD were shown to have reduced phosphorylation levels of PTPN11." (PMID 35802774, 2022). "PTPN family members have been extensively investigated in breast cancer, with PTPN1 and PTPN11 driving the progression of breast cancer." (PMID 35957898, 2022). "Here, we present a list of seven putative genes that are modulated by Rsv in breast cancer in the context of cotreatment with Doxo: HSP90AA1, CCND1, CDH1, ESR1, MAPK3, PTPN11, and RPS6KB1." (PMID 33204396, 2020). "At a molecular level, our in silico analysis suggested that Rsv can modulate two key players of the EMT in breast cancer, Chd1/E-cadherin, and PTPN11/SHP2." (PMID 33204396, 2020). "To examine the requirement for PTPN11 in complex formation in HER2+ breast cancer cells, we analyzed GRB2 and MPZL1 localization in cells depleted of PTPN11." (PMID 28912526, 2017). "As with breast cancer, PTPN1 and PTPN11 also serve as oncogenic factors in lung cancer." (PMID 35957898, 2022). "SHP2 (PTPN11) is required for the full activation of MAPK signaling pathway and could promotes breast cancer (including triple-negative breast cancer) progression." (PMID 33246450, 2020). "Likewise, the dependency on PTPN11 (SHP2) was noticeably more selective in TCGADEPMAP than DEPMAP, which was reflected by greater essentiality in a subset of patients with breast cancer (BRCA) that was absent from BRCA cell lines." (PMID 39009815, 2024).